COPB2 (coat protein complex I subunit beta 2)
Diseases named in the same sentence as COPB2 in open-access papers (continued):
Sharing a sentence is not in itself a finding about the gene and the disease.
tumor (22 papers, 2013 to 2026). "Higher COPB2 expression was associated with larger tumor diameter and higher staging in both the training and validation groups (p < 0.05)." (PMID 40191726, 2025). "In our cohort, a considerable association was found between COPB2 expression and indicators of tumor immune microenvironment (TIME), such as histocompatibility complex class (MHC) I, and MHC II, CD4+/ CD8+ tumor-infiltrating lymphocytes." (PMID 35454945, 2022). "The tumor samples were divided into high- and low-expression groups based on the expression levels of COPB2 and the association between COPB2 expression and prognostic significance with different cancer types derived from TCGA database." (PMID 34676262, 2021). "COPB2 is regarded as a vital oncogene in several cancer types and has been implicated in tumor cell proliferation, survival, invasion, and metastasis." (PMID 34101128, 2021). "Because malignant proliferation of cancer cells is the most important mechanism underlying tumor formation, controlling the proliferation of cancer cells by regulating COPB2 would be a major step in the treatment of cancer." (PMID 34101128, 2021). "Subsequently, the GEPIA2 tool was used to assess all TCGA tumor expression data in order to obtain the top 100 genes associated with COPB2 expression." (PMID 34676262, 2021). "As a coatomer protein, COPB2 plays a major role in embryonic development and tumor progression and is associated with multiple pathological processes." (PMID 34101128, 2021). "Bhandari et al6 reported that the upregulation of COPB2 in breast cancer is associated with age and lymph node metastasis in a validated cohort and promotes tumor cell proliferation and invasion." (PMID 31710183, 2020). "The multivariate Cox analysis identified COPB2 remained independently associated with OS, with a HR of 1.05 (CI: 1.01‐1.08, P = .006), along with tumor status." (PMID 31710183, 2020). "COPB2 is a coatomer subunit and its knock down has already been linked to disabled autophagy and reduced tumor growth." (PMID 28415695, 2017). "Notably, the proteins captured by AC-NP included several frequently mutated proteins in MC38 tumor cells, such as Hnrnpf, Aatf, Copb2, and Kpna6 53,54." (PMID 40379691, 2025). "Results suggested that loss of expression of COPB2 inhibited tumor growth." (PMID 34150620, 2021). "Besides, logistic analysis illustrated in BC patient COPB2 expression, tumour size, age, ER and disease stage were independent high‐risk factors of LNM." (PMID 31119859, 2019). "COPB2's role in apoptosis and tumor growth suppression, may help explain the association of improving vitamin D status in cancer prevention." (PMID 23527013, 2013). "In conclusion, COPB2 acts as an oncogene in GC, driving tumor progression through modulation of the cell cycle and key signaling pathways, highlighting its potential as a therapeutic target." (PMID 41618837, 2026). "The proportion of OS importance accounted for by risk factors of TNM staging, degree of tumor differentiation, YAP1 expression, COPB2 expression, tumor number, and tumor size in the ANN model was 0.23, 0.2168, 0.1823, 0.1338, 0.1288, and 0.1083, respectively." (PMID 40191726, 2025). "Experimental studies have shown that chrysin can inhibit tumor progression by regulating the H19/let-7a/COPB2, P38-MAPK/Akt and Akt/mTOR pathways and affecting mitochondrial function and ER stress." (PMID 38742934, 2024). "Depletion of COPA or COPB2, using two independent shRNAs targeting each gene, impaired the ability of irradiated, senescent fibroblasts to promote the growth of 5PT tumour cells in this setting." (PMID 38012402, 2023). "COPB2, a transporter protein, has been shown to play a key role in embryonic development and tumor progression." (PMID 36768878, 2023). "The volume of tumor nodules was significantly decreased in the COPB2 knockdown group compared with that in the control group in A431 cells." (PMID 35454945, 2022).
tumor (continued). "COPB2 is involved in material transport, energy metabolism as a vesicular envelope protein and tumor progression." (PMID 35600351, 2022). "COPB2 is viewed as a vital oncogene in many cancer types that regulates multiple biological behaviors of tumor cells, including proliferation, survival, tumorigenesis, invasion, and metastasis." (PMID 34101128, 2021). "GSEA results showed that overexpression of COPB2 positively correlated with the activation of many tumor-related pathways in HCC." (PMID 33824874, 2021). "Knockout of the COPB2 gene was generated using the CRISPR/Cas9 system for tumor growth analysis in vivo." (PMID 34150620, 2021). "COPB2 acted as a tumor promoter in the majority of the tumors investigated and can be a potential marker of cancer prognosis." (PMID 34676262, 2021). "GSEA showed that mTOR and other tumor-related signaling pathways were differentially enriched in the high COPB2 expression phenotype." (PMID 33824874, 2021). "This is considered the first pan-tumor study, which provided a relatively comprehensive understanding of the mechanism by which COPB2 promotes cancer growth." (PMID 34676262, 2021). "The majority of the cancer types overexpressed the COPB2 protein, and its expression significantly correlated with tumor prognosis." (PMID 34676262, 2021). "The differences in the levels of COPB2 phosphorylation between tumor tissues and the corresponding normal tissues were examined." (PMID 34676262, 2021). "The mRNA expression levels of specific cancer cell lines were examined using the Cancer Cell Line Encyclopedia (CCLE), and the data indicated that COPB2 expression levels were highly expressed in almost all tumor cell lines, notably neurological tumors." (PMID 34676262, 2021). "The results indicated that the expression of COPB2 was significantly correlated with the pathological stages and tumor differentiation." (PMID 33211699, 2020). "Compared to paracancerous tissues, the expression of COPB2 was up-regulated in tumor tissues (***P<0.001)." (PMID 33211699, 2020). "COPB2 expression levels were correlated with advanced clinicopathological parameters (high grade, histological type, tumor status, age, vital status, and KPS) and a shorter survival time." (PMID 31710183, 2020). "First, more tumour samples are needed to analyse the correlation of COPB2 with clinical parameters and confirm its role in BC metastasis." (PMID 31119859, 2019). "In the TCGA cohort, logistic analysis illustrated in BC patient COPB2 expression, tumour size, age, oestrogen receptor and disease stage were independent high‐risk factors of LNM." (PMID 31119859, 2019). "By chi-square test, we found that COPB2 expression was significantly associated with tumor size and TNM staging in HCC patients, and YAP1 expression was significantly correlated with the degree of tumor differentiation and TNM staging in HCC patients." (PMID 40191726, 2025). "In addition, COPB2 is abnormally highly expressed in many tumor tissues, including colon cancer, prostate cancer, and gallbladder cancer." (PMID 40191726, 2025). "Moreover, COPB2 depletion prevented the senescence-fuelled increase in tumour growth in a xenograft cancer model." (PMID 38012402, 2023). "In the present study, we found that COPB2 may act as a potential oncogene and modulator of the tumor immune microenvironment in cSCC pathogenesis." (PMID 35454945, 2022). "Moreover, a considerable association was found between COPB2 expression and the indicators of TIME, such as MHC class I (MHC I), MHC class II (MHC II), CD4+ tumor-infiltrating lymphocytes (TILs), and CD8+ TILs in our cohort." (PMID 35454945, 2022). "As TGF-β signaling was involved in tumor invasion, COPB2 might induce the invasion of PCa cells through downstream TGF-β signaling pathways." (PMID 35600351, 2022). "In addition, IHC staining indicated that COPB2 expression in the shCOPB2 group was significantly lower than shCtrl group in tumor tissues." (PMID 35600351, 2022).
tumor (continued). "Finally, COPB2 appeared high-expression in tumor tissues of advanced LSCC patients based on immunohistochemistry staining." (PMID 35715770, 2022). "Furthermore, COPB2 is not only involved in vesicle transport, but also participates in the development of tumor cells as an oncogene." (PMID 35600351, 2022). "Knocking down COPB2 expression inhibited the growth and clonogenesis of PCa cells, promoted cell apoptosis, and inhibited the ability of scratch repair, invasion of PCa cells, and tumor growth in Nude mice." (PMID 35600351, 2022). "COPB2 interacted with NUPR1, which was a transcription factor associated with cancer development and advancement; NUPR1 produced a marked effect in cellular stress response and participated in tumor metastasis." (PMID 35600351, 2022). "Together, these data confirmed that COPB2 knockdown inhibited PCa tumor growth in vivo." (PMID 35600351, 2022). "Our results indicated that COPB2 KO suppressed tumor growth." (PMID 34150620, 2021). "However, it is noteworthy that the expression levels of COPB2 were decreased with the increasing tumor stage in OV patients." (PMID 34676262, 2021). "More importantly, COPB2 plays key roles in embryonic development and tumor progression." (PMID 34101128, 2021). "Overall, these results indicate that reduced expression of COPB2 leads to anti-tumor effects." (PMID 34150620, 2021). "The results showed that chrysin is able to inhibit tumor growth and COPB2 expression in vivo." (PMID 34150620, 2021). "In conclusion, COPB2 indicated a pattern of upregulation in the majority of the cancer types, suggesting that it may be a potential tumor promoter." (PMID 34676262, 2021). "Considering the significant dysregulation of COPB2 expression in certain cancer types and its correlation with the tumor stage, it was speculated that this protein may be used as a cancer prognostic indicator." (PMID 34676262, 2021). "The present study demonstrated that COPB2 could affect multiple mechanisms that participated in tumor progression." (PMID 34676262, 2021). "Furthermore, the differences in COPB2 methylation levels between tumor tissues and corresponding normal tissues were assessed." (PMID 34676262, 2021). "This study suggests that chrysin exhibited anti-tumor effects through a H19/let-7a/COPB2 axis." (PMID 34150620, 2021). "In addition to the level of COPB2 phosphorylation, the correlation between COPB2 methylation and tumor incidence was examined." (PMID 34676262, 2021). "The lower degree of tumor differentiation was the stronger COPB2 expressed (*P<0.05 or ***P<0.001)." (PMID 33211699, 2020). "It suggested that COPB2 gene silencing may induce tumor cell apoptosis through the mitochondrial pathway." (PMID 33211699, 2020). "More important is that the function of COPB2 gene will be further verified in tumor-bearing mice." (PMID 33211699, 2020). "Similarly, the multivariate logistic analysis revealed that COPB2 expression, tumour size, age, ER status and clinical stage were significant high‐risk factors of LNM." (PMID 31119859, 2019). "Finally, in vivo data suggested that COPB2 expression is related to tumor growth." (PMID 34150620, 2021). "At the tumor cell level, PD-L1, VISTA, COPB2, and FOXP3 expression on malignant keratinocytes themselves contribute to bidirectional immunosuppression." (PMID 41562715, 2026). "The results showed that the expression of EMT-related interstitial proteins (Vimentin, N-cadherin, Snail, and FN1) was significantly decreased in the shCOPB2 group, suggesting that COPB2 knockdown significantly inhibited EMT transformation and tumor invasion." (PMID 35600351, 2022). "The expression of COPB2, DCTN4, RYK, TARS, and UIMC1 indicated association with the change of fraction of immune cells in LSCC patients; two genes, COPB2 and RYK, indicated different expression in various tumor stages of LSCC." (PMID 35715770, 2022).
tumor (continued). "For investigating the function of COPB2 in vivo, a tumor xenograft mouse model was constructed using PC3 cells, and the tumor size was measured every 4 days." (PMID 35600351, 2022). "The results of immunohistochemistry analysis showed that COPB2 and RYK appeared brownish-yellow in tumor tissues of advanced LSCC patients." (PMID 35715770, 2022). "The expression levels of COPB2 continued to increase following the increase in the LIHC and SKCM tumor grade, further emphasizing its potential tumor-promoting function in these cancer types." (PMID 34676262, 2021). "Functional analysis of COPB2 conducted in HCT116 and SW480 cells treated with COPB2 siRNA or miR-4461 mimics also showed that the KD of COPB2 inhibits the proliferation, migration, and invasion abilities of CRC cells, suggesting that COPB2 behaves as an oncogene in this tumor." (PMID 39000605, 2024). "Finally, COPB2 and RYK showed high-expression in tumor tissues of advanced LSCC patients." (PMID 35715770, 2022). "GSEA suggested that various signaling pathways closely related to tumor occurrence and development (e.g., mTOR signaling pathway, WNT signaling pathway, VEGF signaling pathway, and NOTCH signaling pathway) were differentially enriched in those with the high COPB2 expression phenotype." (PMID 33824874, 2021). "In conclusion, two genes, COPB2 and RYK were found to be significantly correlated with tumor stages of LSCC and represented negative correlation with overall survival of LSCC patients." (PMID 35715770, 2022).
cancer (21 papers, 2012 to 2025). A tumor composed of atypical neoplastic, often pleomorphic cells that invade other tissues. "COPB2 is involved in tumorigenic processes as a proto-oncogene that has been implicated in the proliferation of cancer cells." (PMID 34101128, 2021). "The results of the present study further suggest for the first time the link between COPB2 expression and the immune infiltration of cancer-associated fibroblasts in certain tumors." (PMID 34676262, 2021). "For example, based on the MCPCOUNTER algorithm, the COPB2 expression of CESCs was positively associated with the infiltration level of cancer-associated fibroblasts (cor = 0.199, P = 9.86e − 4)." (PMID 34676262, 2021). "The outcomes indicated that COPB2 expression levels were significantly associated with the clinical stage of the following cancer types: LIHC (P = 0.0165), OV (P = 0.0347), and SKCM (P = 0.0394)." (PMID 34676262, 2021). "In the present study, the GEPIA2 tool was used to assess the association of the OS and DFS in patients with high COPB2 expression in pan-cancer tissues." (PMID 34676262, 2021). "GSEA indicated that some immune‐related pathways and other signaling pathways in cancer were associated with the COPB2‐high phenotype." (PMID 31710183, 2020). "COPB2 expression levels are upregulated in several human cancers and are associated with their prognosis." (PMID 31926110, 2020). "Several studies have reported direct and indirect associations between COPB2 and cancer." (PMID 34101128, 2021). "A relatively low overall mutation rate of COPB2 was observed in all cancer types (less than 10%)." (PMID 34676262, 2021). "Furthermore, the potential association between COPB2 gene alterations and the prognosis of different cancer patients was explored." (PMID 34676262, 2021). "We also included gene expression, survival status, gene mutations, protein phosphorylation, immune infiltration, cellular pathways, and chemotherapy sensitivity analyses in order to explore the underlying molecular mechanisms of COPB2 in the pathogenesis of various cancer types." (PMID 34676262, 2021). "COPB2 is thought to be an important oncogene in several cancer types, and its downregulation inhibits cell proliferation, induces G1 phase arrest, and induces the synthesis of mRNA and proteins." (PMID 38674024, 2024). "Recently, COPB2 has been shown to execute a range of oncogenic activities in various types of cancers." (PMID 35454945, 2022). "Consistent with other cancers, we found that COPB2 expression was significantly increased in cSCC tissues compared with that in normal skin tissue samples in both the public database and our cohort." (PMID 35454945, 2022). "There is increasing evidence that coatomer protein complex subunit beta 2 (COPB2) plays an important role in various cancer types." (PMID 35600351, 2022). "In this paper, we focus on the emerging roles of COPB2 in cancer development and progression in the context of the hallmarks of cancer." (PMID 34101128, 2021). "A limited number of studies in recent years have reported the relationship between COPB2 and specific common diseases, notably cancer." (PMID 34676262, 2021). "Current studies have demonstrated that COPB2 is a vital oncogene in many cancer types due to its ability to regulate the proliferation, survival, tumorigenesis, invasion, and metastasis of cancer cells." (PMID 34101128, 2021). "Initially, the expression pattern of COPB2 was analyzed in different cancer types derived from TCGA database by the TIMER method." (PMID 34676262, 2021). "Subsequently, the genetic alterations of COPB2 were investigated among different cancer samples from TCGA database." (PMID 34676262, 2021). "In terms of cancer treatment, we should focus on exploring the role of COPB2 in immunotherapy and targeted therapy." (PMID 34676262, 2021).